AP2M1 (adaptor related protein complex 2 subunit mu 1)
Description:
Component of the adaptor protein complex 2 (AP-2). Adaptor protein complexes function in protein transport via transport vesicles in different membrane traffic pathways. Adaptor protein complexes are vesicle coat components and appear to be involved in cargo selection and vesicle formation. AP-2 is involved in clathrin-dependent endocytosis in which cargo proteins are incorporated into vesicles surrounded by clathrin (clathrin-coated vesicles, CCVs) which are destined for fusion with the early endosome. The clathrin lattice serves as a mechanical scaffold but is itself unable to bind directly to membrane components. Clathrin-associated adaptor protein (AP) complexes which can bind directly to both the clathrin lattice and to the lipid and protein components of membranes are considered to be the major clathrin adaptors contributing the CCV formation. AP-2 also serves as a cargo receptor to selectively sort the membrane proteins involved in receptor-mediated endocytosis. AP-2 seems to play a role in the recycling of synaptic vesicle membranes from the presynaptic surface. AP-2 recognizes Y-X-X-[FILMV] (Y-X-X-Phi) and [ED]-X-X-X-L-[LI] endocytosis signal motifs within the cytosolic tails of transmembrane cargo molecules (By similarity). AP-2 may also play a role in maintaining normal post-endocytic trafficking through the ARF6-regulated, non-clathrin pathway. During long-term potentiation in hippocampal neurons, AP-2 is responsible for the endocytosis of ADAM10. The AP-2 mu subunit binds to transmembrane cargo proteins; it recognizes the Y-X-X-Phi motifs (By similarity). The surface region interacting with to the Y-X-X-Phi motif is inaccessible in cytosolic AP-2, but becomes accessible through a conformational change following phosphorylation of AP-2 mu subunit at Thr-156 in membrane-associated AP-2. The membrane-specific phosphorylation event appears to involve assembled clathrin which activates the AP-2 mu kinase AAK1. Plays a role in endocytosis of frizzled family members upon Wnt signaling (By similarity).
Synonyms: CLAPM1; AP50; mu2; MRD60
Tractability: Antibody: UniProt places it where antibodies can reach, with high confidence; its Gene Ontology location is reachable by antibodies, with high confidence; the Human Protein Atlas places it where antibodies can reach. PROTAC: ubiquitination databases record sites on it; its protein half-life has been measured.
Gene: Protein-coding gene on chromosome 3 (184,174,689 to 184,184,214, forward strand). Ensembl gene ENSG00000161203.
Subcellular location: Cell membrane; Membrane, coated pit
Subcellular location (Human Protein Atlas): Plasma membrane
Pathways (Reactome):
Disease: Dengue Virus Attachment and Entry; Nef Mediated CD4 Down-regulation; Nef Mediated CD8 Down-regulation; Nef mediated downregulation of CD28 cell surface expression; Potential therapeutics for SARS
Vesicle-mediated transport: Cargo recognition for clathrin-mediated endocytosis; Clathrin-mediated endocytosis; Formation of annular gap junctions; Gap junction degradation
Signal Transduction: Retrograde neurotrophin signalling; WNT5A-dependent internalization of FZD2, FZD5 and ROR2; WNT5A-dependent internalization of FZD4
Developmental Biology: EPH-ephrin mediated repulsion of cells; Recycling pathway of L1
Transport of small molecules: LDL clearance; VLDLR internalisation and degradation
Immune System: MHC class II antigen presentation
Neuronal System: Trafficking of GluR2-containing AMPA receptors
Gene Ontology:
Molecular function: clathrin adaptor activity; protein binding; signal sequence binding; transmembrane transporter binding; low-density lipoprotein particle receptor binding
Biological process: clathrin-dependent endocytosis; negative regulation of protein localization to plasma membrane; receptor internalization; regulation of vesicle size; synaptic vesicle endocytosis; vesicle budding from membrane; Golgi to vacuole transport; postsynaptic neurotransmitter receptor internalization; protein-containing complex assembly; vesicle-mediated transport; intracellular protein transport; positive regulation of receptor internalization; positive regulation of synaptic vesicle endocytosis; vesicle-mediated transport in synapse
Cellular component: AP-2 adaptor complex; clathrin-coated pit; extracellular exosome; plasma membrane; clathrin-coated endocytic vesicle; clathrin-coated endocytic vesicle membrane; cytoplasmic side of plasma membrane; cytosol; endocytic vesicle membrane; endolysosome membrane; lysosomal membrane; synaptic vesicle; clathrin adaptor complex; extrinsic component of presynaptic endocytic zone membrane; glutamatergic synapse; membrane; postsynapse
Genetic constraint (gnomAD): Loss-of-function variants: 5 observed, 57.7 expected, observed/expected ratio (o/e) 0.0867, 90% interval 0.044 to 0.18. The upper end of that interval is the gene's LOEUF score, 0.18, which puts it in group 1 of 6, group 1 being the genes least tolerant of losing a copy. Missense variants: 178 observed, 607.85 expected, observed/expected ratio (o/e) 0.29, 90% interval 0.26 to 0.33. Synonymous variants: 186 observed, 219.51 expected, observed/expected ratio (o/e) 0.85, 90% interval 0.75 to 0.96.
Gene-disease validity (ClinGen):
ClinGen rates the evidence that AP2M1 causes each of these diseases.
complex neurodevelopmental disorder (autosomal dominant): Definitive. A disorder that involves more than one phenotype associated with the central nervous system, including but not limited to intellectual disability, autism, and seizures (epilepsy).
Homologues: Orthologues: dog AP2M1 (100% identical), guinea pig AP2M1 (100% identical), macaque AP2M1 (100% identical), mouse Ap2m1 (100% identical), pig AP2M1 (100% identical), rabbit AP2M1 (100% identical), rat Ap2m1 (100% identical), chimpanzee AP2M1 (99% identical), tropical clawed frog ap2m1 (99% identical), zebrafish ap2m1b (98% identical), zebrafish ap2m1a (98% identical). Paralogues in human: AP1M1 (40% identical), AP1M2 (39% identical), AP4M1 (26% identical), AP3M2 (25% identical), AP3M1 (24% identical), STON2 (22% identical), STON1 (19% identical).
Diseases named in the same sentence as AP2M1 in open-access papers:
AP2M1 is named in the same sentence as 53 diseases in open-access papers, as found by Europe PMC text mining. Sharing a sentence is not in itself a finding about the gene and the disease. The quoted sentences say what the papers report.
breast cancer (5 papers, 2023 to 2025). A primary or metastatic malignant neoplasm involving the breast. "Increased AP2M1 activity has been associated with chemotherapy resistance in several tumor types, including lymphoma, breast cancer and CRC." (PMID 38188020, 2023). "In breast cancer models, polypropylene increased AP2M1, PTP4A2, and TMBIM6 while reducing FTH1, a pattern consistent with enhanced trafficking/ER-stress signaling and diminished iron-mediated tumor suppressive functions." (PMID 41378310, 2025). "For breast cancer, miR-483-3p and miR-138-5p showed favorable predictions against ABCB1/PTP4A2 and TMBIM6, respectively, while miR-365 and miR-331-3p mapped to ABCG2/AP2M1." (PMID 41378310, 2025). "We also found that the gene expression of TMBIM6, AP2M1, and PTP4A2, which are correlated with cancer progression and the cell cycle, was significantly increased by PPMP incubation in MDA-MB-231 human breast cancer cells, suggesting that PPMPs regulate the transcriptional activity of cancer cells." (PMID 37069244, 2023).
epilepsy (4 papers, 2021 to 2025). A brain disorder characterized by episodes of abnormally increased neuronal discharge resulting in transient episodes of sensory or motor neurological dysfunction, or psychic dysfunction. "In the case of AP2M1-DEE, our findings suggest that the developmental consequences of AP2M1 loss of function may underlie the more substantial burden of the human disease phenotype, with epilepsy possibly being a secondary phenomenon resulting from defects of neuronal development." (PMID 41017589, 2025). "In the gene AP2M1, the recurrent de novo variant c.508C>T (p.Arg170Trp) (GenBank: NM_004068.3) has been detected in four individuals with DEE, featuring a DEE subtype of epilepsy with myoclonic-atonic seizures." (PMID 41017589, 2025). "Finally, a novel de novo heterozygous variant (AP2M1:c.73G>A, p.Gly25Arg) was found in a 3‐year‐old boy with GDD, macrocephaly, and multifocal epileptiform activity on EEG without epilepsy." (PMID 40719069, 2025).
viral infection (4 papers, 2021 to 2024). "To identify the mechanistic details of sunitinib-mediated inhibition of TOSV entry, we probed the levels of phospho-AP2M1 following viral infection treatment." (PMID 39017647, 2024). "Furthermore, wild-type AP2M1 partially rescued viral infection when a low (2 μM) dose of sunitinib was used." (PMID 39017647, 2024). "Thus, to confirm that the inhibition is mediated through phospho-AP2M1 we tested if overexpression of AP2M1 could compensate for the lack of phosphorylation and rescue viral infection." (PMID 39017647, 2024).
hepatocellular carcinoma (3 papers, 2020 to 2023). A malignant tumor that arises from hepatocytes. "The first of these genes, AP-2 complex subunit mu (AP2M1) was found to be a promising biomarker for predicting survival of patients with hepatocellular carcinoma." (PMID 36979661, 2023). "A recent study indicated that AP2M1 was overexpressed in adenoid cystic and mucoepidermoid carcinomas and could serve as a prognostic marker of hepatocellular carcinoma." (PMID 35610596, 2022). "AP2M1 can also serve as a prognostic marker of hepatocellular carcinoma." (PMID 32943990, 2020).
autism spectrum disorder (2 papers, 2025). A spectrum of developmental disorders that includes autism, and Asperger syndrome. "A missense mutation in AP2M1 impairs CME and causes epileptic and developmental encephalopathy, and the CNV of AP2M1 may contribute to the risk of autism spectrum disorders." (PMID 41153917, 2025).
Epileptic encephalopathy (2 papers, 2019 to 2025). A condition in which epileptiform abnormalities are believed to contribute to the progressive disturbance in cerebral function. "However, milder mutations in the genes encoding AP-2σ (AP2S1) and AP-2μ (AP2M1) have been identified as cause for familial hypocalciuric hypercalcemia (FHH) type 3 respectively epileptic encephalopathy." (PMID 31671891, 2019). "A de novo missense mutation in AP2M1 (p.Arg170Trp) was recently identified in a comprehensive approach based on whole exome sequencing data of a cohort of 314 individuals suffering from epileptic encephalopathies paired with an analysis of their phenotypic similarities." (PMID 31671891, 2019).
lung carcinoma (2 papers, 2013 to 2020). "Finally, AP2M1, found in lung cancer cell line TAP and also identified with wild-type EGFR in AALE cells, was chosen as a representative member of adapter proteins important in EGFR endocytosis." (PMID 24189400, 2013). "Many new targets of IgGs in lung cancer were non-cell surface proteins, but we noticed that many targets of these IgGs were adaptor proteins, such as the AP-2 complex including AP2A1, AP2A2, AP2B1, AP2S1, and AP2M1." (PMID 32580738, 2020).
mucoepidermoid carcinoma (2 papers, 2020 to 2022). A carcinoma morphologically characterized the presence of cuboidal mucous cells, goblet-like mucous cells, squamoid cells, cystic changes, and a fibrotic stromal formation. "In addition, AP2M1 is positively associated with cyclin D1 in adenoid cystic carcinoma (AdCC) and mucoepidermoid carcinoma (MEC), indicating that AP2M1 are involved in the proliferation of AdCC and MEC to cause tumor growth." (PMID 32943990, 2020).
prostate carcinoma (2 papers, 2018 to 2020). A carcinoma that arises from epithelial cells of the prostate gland. "Some studies have shown that AP2M1 is related to the occurrence and development of cancers, including medulloblastoma, head and neck squamous cell carcinoma, esophageal squamous cell carcinoma, chronic myeloid leukemia, prostate cancer and HCC." (PMID 32943990, 2020).
Alzheimer disease (1 paper, 2022). A progressive, neurodegenerative disease characterized by loss of function and death of nerve cells in several areas of the brain leading to loss of cognitive function such as memory and language. "We discovered that a down-regulated circRNA (has_circ_002048) caused the increased expression of numerous miRNAs, which further inhibited the expression of a critical mRNA (AP2M1), leading to Alzheimer’s disease pathology." (PMID 36468008, 2022). "In KEGG gene sets, GSEA results show that AP2M1 is mainly enriched in glycosphingolipid biosynthetic ganglion series, Parkinson’s disease, Alzheimer’s disease, β-Alanine metabolism, and axonal guidance mechanism." (PMID 36468008, 2022). "In conclusion, we suspect that AP2M1 may be regulated by the circRNA-miRNA-mRNA network, which has an important impact on Alzheimer’s disease." (PMID 36468008, 2022).
autism (1 paper, 2023). Persistent deficits in social interaction and communication and interaction as well as a markedly restricted repertoire of activity and interest as well as repetitive patterns of behavior. "Notably, some constrained genes such as AP2M1 and CACNG2, reported in individuals with cognitive impairment, displayed autism ORs >10 without being included in the lists of autism-associated genes (for example SFARI and SPARK genes)." (PMID 37365347, 2023).
dengue virus infection (1 paper, 2020). "AP2M1 is required for hepatitis C, rabies and dengue virus infection, and AP2M1 knockdown reduces the viral titer or infectivity." (PMID 32943990, 2020).
developmental and epileptic encephalopathy (1 paper, 2025). An epilepsy associated with developmental impairment that may be due to either the underlying etiology or the superimposed epileptic activity, or both. "Genetic defects in AP2M1, which encodes the μ-subunit of the adaptor protein complex 2 (AP-2) essential for clathrin-mediated endocytosis, cause a rare form of developmental and epileptic encephalopathy (DEE)." (PMID 41017589, 2025).
disc degeneration (1 paper, 2026). "In vitro experiments demonstrated that overexpression of HLA-A or AP2M1 promoted nucleus pulposus cell proliferation, suppressed apoptosis, and enhanced endocytic activity, whereas in vivo overexpression alleviated disc degeneration in a rat model." (PMID 41696752, 2026). "Collectively, these findings identify HLA-A and AP2M1 as potential biomarkers linking immune dysregulation and endocytic dysfunction in IVDD and provide new insights into the molecular mechanisms underlying disc degeneration." (PMID 41696752, 2026).
glomerulosclerosis (1 paper, 2024). A hardening of the kidney glomerulus caused by scarring of the blood vessels. "The mutation, associated with glomerulosclerosis (metabolic disease) and enhanced channel activity, is found at the p + 2 position of the YxxΦ-motif of AP2M1." (PMID 39009827, 2024).
laryngeal carcinoma (1 paper, 2019). Carcinoma that arises from the laryngeal epithelium. "A comparison of the prognosticators identified for tongue and laryngopharynx indicated that AP2M1 and IGF2BP2 are common across sites, with deregulation of AP2M1, a protein trafficking molecule, signifying contradictory effects in tongue and laryngeal cancer." (PMID 31310629, 2019).
melanoma (1 paper, 2016). A malignant, usually aggressive tumor composed of atypical, neoplastic melanocytes. "Therefore, it is reasonable to expect that the adaptor protein AP2M1 mediate the in vivo uptake of ASO-1560S in B16F10 melanoma cells." (PMID 27507060, 2016).
myopia (1 paper, 2016). "Mutations in this gene are associated with nonsyndromic severe myopia and cataract.AP2M1 (adaptor-related protein complex 2, mu 1 subunit, Gene ID: 1173) gene is also involved in several biological processes and participates in the epidermal growth factor receptor (EGFR) signaling pathway." (PMID 27007896, 2016).
Oppositional defiant disorder (1 paper, 2025). An enduring pattern of uncooperative, defiant, and hostile behavior towards authority figures that does not involve major antisocial violations, is not accounted for by the child's developmental stage, and results in significant functional impairment. "We report an individual carrying a novel de novo AP2M1 variant with attention‐deficit/hyperactivity disorder (ADHD), oppositional defiant disorder, and unexpected hemiplegic migraine (HM)." (PMID 40719069, 2025).
papillary thyroid cancer (1 paper, 2024). "Of significance, AP2A1, AP2B1 and AP2M1 were highly expressed in papillary thyroid cancer (PTC) with the more aggressive BRAF-like gene signature compared to RAS-like PTC, as well as in the independent PTC dataset GSE60542." (PMID 37921808, 2024).
SARS-CoV infection (1 paper, 2020). "In the current study, we used SARS-CoV pseudotyped virus (HIV/SARS-CoV pseudovirus) to screen a siRNA library, and identified AP2M1 as a crucial host factor for SARS-CoV infection." (PMID 33083006, 2020). "The siRNA library used for screening is an intracellular membrane traffic siRNA library targeting 144 host molecules, and the primary screening results suggested that AP2M1 may play an important role in SARS-CoV infection." (PMID 33083006, 2020).
tongue cancer (1 paper, 2019). A malignant neoplasm affecting the tongue. "Early stage tongue cancer patients were significantly classified into patients with poor/good survival based on alterations in AP2M1, CTBP1, and MTFR1 all of whom were associated with prognosis in other studies." (PMID 31310629, 2019).